FRS2 (fibroblast growth factor receptor substrate 2)
Diseases named in the same sentence as FRS2 in open-access papers (continued):
Sharing a sentence is not in itself a finding about the gene and the disease.
tumor (continued). "In order to evaluate the occurrence of activated FGFR2 signalling in the tumor tissue of iCCA patients with FGFR2 GAs, we assessed the levels of protein phosphorylation of both FGFR2 and FRS2α, its main downstream target." (PMID 38326380, 2024). "We do not have evidence that unequivocally supports a functional role for the FRS2 and PLEKHA5 fusion events, and further studies are warranted to determine their role in tumour progression." (PMID 39322633, 2024). "To conclude, we provide strong evidence that compound 7 interference with FRS2 functions, represses oncogenic FGFR signaling and invasiveness in human cancer cells and can reduce tumor growth in vivo." (PMID 36495366, 2023). "The here identified bioactive leads targeting FGF signaling and cell dissemination provide a novel structural basis for further development as a tumor agnostic strategy to repress FGFR- and FRS2-driven tumors." (PMID 36495366, 2023). "This unexpected crosstalk between these RTKs for FRS2 phosphorylation and TNBC TICs is further supported by in vivo studies where tumour initiation was inhibited only upon combination therapy with Met and FGFR inhibitors." (PMID 33772015, 2021). "M60 tumor exhibited two chromosome 12 loci resulting in high gene overexpression, including of MDM2, YEATS4 and FRS2." (PMID 33853673, 2021). "We demonstrate a requirement for the scaffold protein FRS2 downstream from both Met and FGFR1 and find that dual inhibition of MET and FGFR1 signalling results in TIC depletion, hindering tumour progression." (PMID 33772015, 2021). "The expression of FRS2 was also compared with that of classic immunomarkers (MDM2 and CDK4) of this tumor entity." (PMID 34696768, 2021). "We investigated the profiles for six protein markers, FGFR1, FRS2, S6K1, LDHB, MYPT1, and P-LDHA, in tumor-adjacent stroma." (PMID 31316912, 2019). "In PCa, elevated autocrine fibroblast growth factor 2 (FGF-2) promotes tumor cell growth by stimulating DNA synthesis, ERK1/2, AKT and FRS-2α (fibroblast growth factor receptor substrate-2)." (PMID 29732010, 2018). "Lenvatinib inhibited in vivo tumor growth in Hep3B2.1‐7 and SNU‐398 xenografts and decreased phosphorylation of FRS2 and Erk1/2 within the tumor tissues." (PMID 29733511, 2018). "The positive rates in tumor regions for GAB2, CRKL, and FRS2 were 40.00% (30/75), 53.95% (41/76), and 35.06% (27/77), respectively." (PMID 28558797, 2017). "The dodecasaccharide reduced the number of phospho-FRS2-positive blood vessels by 47%, showing that [NSIS6S]-[NSIS]5 is an effective inhibitor of FGF2-mediated tumor angiogenesis." (PMID 27490176, 2016). "Exploratory biomarker analysis of an archival tumour sample showed clear evidence of high FGFR, FGF-ligand and FRS2 expression." (PMID 26497743, 2015). "We show that the combination of dovitinib with the PI3K/mTOR inhibitor, NVP-BEZ235, strongly downregulates the FRS2/extracellular signal-regulated kinase (Erk) and PI3K/Akt/mTOR signaling pathways, resulting in high levels of apoptosis and tumor stasis." (PMID 23343422, 2013). "The MSKCC Prostate Oncogenome Project was interrogated for FRS2 and FRS3 transcript expression (n = 131 primary tumours with mRNA data available) using the cBio Cancer Genomics Portal." (PMID 22078327, 2011). "Nevertheless, they do suggest the potential for using FRS2 and FRS3 as a target to achieve selective enhancing of radio-toxicity in tumours with relative sparing of benign tissue." (PMID 22078327, 2011). "Five miRNAs (19b, 29a, 29b, 29c and 148a) shared 70 predicted targets, some of which (CDK6, PTEN, IGF1, FRS2, PDGFRA, PIK3R1 and MXD1) regulate cellular proliferation and tumor suppression." (PMID 20949028, 2010). "Targeting FGFR signaling downstream at FRS2α may suppress FGFR-dependent tumor cells and limit CAF-mediated pro-tumor support while sparing a subset of CAFs, providing experimental support for CAF-aware strategies to target the FGFR pathway." (PMID 41514658, 2025).
tumor (continued). "To further investigate the expression levels of FRS2, we analyzed tumor datasets from the TCGA database alongside corresponding normal tissues from the GTEx cohort using GEPIA2." (PMID 40225873, 2025). "FRS2 interacts with FGFRs via its phosphotyrosine-binding (PTB) domain and increased expression or activation of FRS2 is involved in tumorigenesis of several tumor entities." (PMID 36495366, 2023). "In our study, all 18 tested WDLs were 12q13-15 amplified, including 17 MDM2-amplified cases and 1 FRS2-amplified/MDM2-nonamplified/CDK4-nonamplified tumor (case 4)." (PMID 36059611, 2022). "Depletion of FRS2α expression in human PCa cells and in MDA PCa 118b, a human PCa-derived xenograft, also suppresses tumor angiogenesis, as well as decreases bone metastasis of the tumor." (PMID 30761180, 2019). "Fibroblast growth factor receptor substrate 2 (FRS2) phosphorylation was apparent in tumor specimens from vehicle-treated animals but absent in tumors from BGJ398-treated animals, indicating adequate BGJ398 dose administration." (PMID 26826125, 2016). "Only 6% and 8% of tumours had any changes in FRS2 and FRS3 expression compared to normal controls respectively." (PMID 22078327, 2011). "FISH analysis revealed that the tumor was negative for MDM2/CDK4/FRS2 amplification." (PMID 36059611, 2022). "Phosphorylation of FRS2α, ERK, and AKT, downstream events of FGF21 action, was markedly increased in both non-tumorous and tumorous parts of the liver of Atg7ΔHepFgf21+/+ mice and was abrogated in the liver of Atg7ΔHepFgf21−/− mice." (PMID 35321438, 2022). "FRS2 and FRS3 are not over-expressed in tumours but targeted dual inhibition may selectively adversely affect malignant but not benign prostate cells." (PMID 22078327, 2011).
cancer (32 papers, 2011 to 2025). A tumor composed of atypical neoplastic, often pleomorphic cells that invade other tissues. "We analyzed the mutational landscape of the FRS2 gene across multiple cancer types using the cBioPortal platform." (PMID 40707918, 2025). "This study identified the most common types of FRS2 mutations and assessed FRS2 mRNA expression across various cancers." (PMID 40225873, 2025). "Among the 32 cancer types analyzed, amplification mutations, gain mutations, and shallow deletions were frequently associated with FRS2 mRNA expression across different cancers." (PMID 40225873, 2025). "Beside well-known cancer-associated genes, 6 UBCs had supporting SVs responsible for FRS2 duplication with 3–25-fold increase of gene copy numbers." (PMID 30755618, 2019). "Previous studies have shown that FRS2 is linked to poorer prognosis in various cancers." (PMID 40225873, 2025). "Therefore, abnormal levels of FRS2 are closely associated with the development of cancer, heart disease, and neuronal disorders." (PMID 34414852, 2021). "Future research should focus on FRS2 expression across different cancer subtypes and specific immune profiles to better understand its prognostic value and therapeutic potential." (PMID 40225873, 2025). "The cBioPortal online tool was utilized to analyze genetic variations in FRS2 expression across cancer types." (PMID 40225873, 2025). "Consistent with pan-cancer analyses, our study found high FRS2 expression in 65.9% (54/82) of retroperitoneal liposarcoma (RLPS) specimens." (PMID 40225873, 2025). "FRS2 is a significant prognostic biomarker in various cancers and a promising therapeutic target for RLPS." (PMID 40225873, 2025). "Targeting the FGFR‐specific adaptor protein, FRS2 using a novel FRS2ai has shown to have a specific and anti‐ proliferative effect by disrupting the contact between the CAFs and cancer cells." (PMID 39300962, 2024). "The most relevant FGFR-downstream pathways in cancer are activated by the FGFR substrate 2 (FRS2) mediated binding of growth factor receptor bound protein 2 (GRB2)." (PMID 35955806, 2022). "KLb affects FGF4 signaling pathway, phosphorylation of ERK1/2 and FRS2, resulting in enhancement of cell proliferation or inhibition of cancer cell apoptosis." (PMID 29731962, 2018). "FGF receptor substrate 2 (FRS2) participates in the transmission of extracellular signals from the FGF receptor, and activation of the FGF receptor and phosphorylation of FRS2 are a crucial event for the development of some cancers." (PMID 24265601, 2013). "The aim of this study was to explore whether modulation of FRS2 function by small molecule compound binding is a successful strategy to interfere with FGFR-driven oncogenic functions of cancer cells." (PMID 36495366, 2023). "Enriched pathways for upregulated miRNAs included: “Chemical carcinogenesis–receptor activation” (p-value = 0.018) associated with ESR1, FGF18, JAG1, KPNA6, PPARA genes; the pathway “Proteoglycans in cancer” (p-value = 0.089) associated with genes ESR1, FRS2, HIF1A, PDCD4." (PMID 36359024, 2022). "Whether differential expression of FGFR1/2/3 or the effector FRS2 correlated with sensitivity of cancer cells to FGFR inhibitors remains to be investigated." (PMID 34369083, 2021). "An important therapeutic question is if either FRS2 or FRS3 are over-expressed in cancer." (PMID 22078327, 2011). "Thus, further studies are needed to clarify FRS2's role in other cancers." (PMID 40225873, 2025). "We hypothesized that FRS2-FGFR interactions constitute a potentially druggable PPI with clinical relevance related to oncogenic signaling through FGFRs, where oncogenic alterations including amplification, mutation and fusion are common across human cancers." (PMID 36495366, 2023). "FRS2 amplification is common across 32 cancer types, with nearly 20% of SARC population exhibiting FRS2 amplification, the highest prevalence among all cancer types." (PMID 40225873, 2025).
cancer (continued). "ACTG1, SDC1, FRS2, and WNT9B were commonly identified as genes contributing to the enrichment of the ‘Proteoglycans in Cancer’ pathway in both species." (PMID 41296454, 2025). "Target prediction and functional annotation identified 59 overlapping genes, with the Proteoglycans in cancer pathways being conserved in both species, mediated by ACTG1, SDC1, FRS2, and WNT9B." (PMID 41296454, 2025). "An FGF9 mutant (R108E) was defective in integrin binding, activating FRS2α and ERK1/2, inducing DNA synthesis, cancer cell migration, and invasion in vitro." (PMID 38391921, 2024). "Our study thus warrants further pre-clinical development of 7 for the treatment of human cancers with activated FGFR signaling and oncogenesis driven by the overexpression of FRS2." (PMID 36495366, 2023). "Including fusions previously identified as cancer-related chimera (i.e. FRS2–MDM1, FRS2–PTPRR, CCT2–BEST3, RAB3IP–BEST3) of which both partner genes are overexpressed due to the amplification." (PMID 37400763, 2023). "Repression of FRS2 function was previously explored via the inhibition of the FRS2-directed N-myristoyltransferase, which repressed FGFR signaling, cell proliferation and migration in several cancer types." (PMID 36495366, 2023). "The mechanism behind FGF2’s action includes the phosphorylation of FRS2 which activates the MAPK and PI3K/Akt signaling pathways in both cancer cells and ECs." (PMID 33121202, 2020). "Subsequent phosphorylation of FRS2 activates the Ras-mitogen-activated protein kinase (MAPK), and the PI3K/Akt signaling pathways in cancer cells and ECs, promoting angiogenic processes." (PMID 33121202, 2020). "Taken together we believe that these results justify further studies to investigate FRS2 and FRS3 in FGFR binding and signalling in the prostate and define mechanisms by which FRS2 and FRS3 targeting appears to be more detrimental to cancer cells." (PMID 22078327, 2011). "An important first step however is to determine the relative expression and function of FRS2 and FRS3 in a specific cancer." (PMID 22078327, 2011). "Two genes in this pathway, EPHA3 and FRS2, were designated SCNA-genes in both our dataset and in Stark and Hayward, and were annotated as amplified, in skin-derived tumors, in the Cancer Genome Project dataset." (PMID 21494657, 2011). "Notably, only one pathway, Proteoglycans in cancer (p < 0.05), was conserved across both species, with ACTG1, SDC1, FRS2, and WNT9B identified as common genes participating in this pathway." (PMID 41296454, 2025). "Although FRS2 is not widely expressed in normal tissues, TCGA and GTEx data revealed significantly higher expression levels in most cancers compared to corresponding normal tissues." (PMID 40225873, 2025). "In addition, we tested a novel concept of targeting fibroblast growth factor receptor substrate 2 (FRS2α), which integrates FGFR signaling from all four FGFR receptors in normal and cancer cells." (PMID 39300962, 2024). "Thus, according to MirAnalyze database, let-7a-5p, miRNA-16-5p, -21-5p share common target genes as follows: B-cell translocation gene 2 (BTG 2), and fibroblast growth factor receptor substrate 2 (FGFR2), which change their expression in cancer." (PMID 34434498, 2021). "Platelet activation, focal adhesion, proteoglycans in cancer, axon guidance, phagosome, glutamatergic synapse and MAPK1, FRS2, FDGFRA, SHC1, ITGB2 and ITGA1 may be the core bio-pathway and genes involved in direct intervention, respectively." (PMID 28380454, 2017). "Preliminary results of down-regulation in combination with a cytotoxic therapy however do suggest that targeting FRS2 and FRS3 may be specifically effective in cancer cells." (PMID 22078327, 2011). "We also tested if with increasing cancer grades there was any evidence of a progressive increase or decrease in expression and found no significant alterations (p = 0.23 for FRS2 and p = 0.87 for FRS3)." (PMID 22078327, 2011).
cancer (continued). "We also show that neither FRS2 nor FRS3 are apparently over-expressed in cancer and acknowledge that this does limit their attractiveness as a therapeutic target." (PMID 22078327, 2011). "In contrast to cancer cells, the clonogenic survival after radiation between scramble and siRNA FRS2 and FRS3 cells was not significantly different in these benign epithelial cell lines." (PMID 22078327, 2011). "Additionally, five cancer cell lines without FRS2 amplification, based on the CCLE database, were tested." (PMID 40707918, 2025). "Abnormal FRS2 expression in specific cancer subtypes might not be reflected in broader cancer populations." (PMID 40225873, 2025). "Additionally, FRS2 could play a role in immune cell infiltration in SARC and represents a promising immunotherapeutic target for cancer treatment." (PMID 40225873, 2025). "Silencing FRS2 and FRS3 had a profound effect on FGF induced proliferation, migration and invasion regardless of the FGF ligand used and in two different cancer cell lines." (PMID 22078327, 2011). "Despite the lack of over-expression we did observe that FRS2 and FRS3 suppression had a significant and specific inhibitory effect in cancer cell lines whereas it had no discernible effect on PNT2 benign prostate cells which are known to express FGF receptors and respond to FGF stimulation." (PMID 22078327, 2011). "Thus while FRS2 and FRS3 may not be over-expressed in cancer, they may still conceivably be a viable target if their inhibition is selectively effective in cancer but not benign cells." (PMID 22078327, 2011).
infection (2 papers, 2019 to 2023). The state of being infected such as from the introduction of a foreign agent such as serum, vaccine, antigenic substance or organism. "Intriguingly, the engagement of FGF-bound EBs with FGFR activated downstream signaling: phosphorylation of the FGFR substrate and docking protein FRS2α was increased by infection, and phosphorylated FRS2α was recruited to sites of EB attachment." (PMID 31877733, 2019). "The regulatory networks miRNs–mRNA showed that FRS2 and AP1S2 target genes interacted with gga-miR-204 and gga-miR-1729-5p, while HHIP target gene is regulated by two miRNAs, gga-miR-19b-3p and gga-miR-132a-3p, at 7 days post-infection." (PMID 38288128, 2023).
prostate (1 paper, 2025). "Consistently, FRS2 knockdown has been reported to actas a repressor of protein kinase D1, leading to inhibition of prostate cancerprogression." (PMID 40834280, 2025).
FRS2 also shares sentences with these, for which no sentence is quoted: lung adenocarcinoma (3 papers); acute myeloid leukemia (1); angiosarcoma (1); atypical lipomatous tumor (1); breast tumor (1); cardiac hypertrophy (1); dedifferentiated liposarcoma (1); endometrial carcinoma (1); giant cell tumor (1); heart disease (1); hemangioblastoma (1); hepatocellular carcinoma (1); myeloma (1); ovarian adenocarcinoma (1); renal cell carcinoma (1); rhabdomyosarcoma (1); Salmonella Infections (1); spindle cell lipoma (1); triple-negative breast carcinoma (1); undifferentiated pleomorphic sarcoma (1).